AQP4 (aquaporin 4)
Diseases named in the same sentence as AQP4 in open-access papers (continued):
Sharing a sentence is not in itself a finding about the gene and the disease.
inner ear diseases (2 papers, 2018 to 2026). "The hearing impairment in NMOSD might also be associated with inflammation of the inner ear; i.e., AQP4 antibodies likely cause a form of “labyrinthitis”." (PMID 41598359, 2026).
intracranial hemorrhage (2 papers, 2012 to 2022). Bleeding within the SKULL, including hemorrhages in the brain and the three membranes of MENINGES. "BBB breakdown increases the expression of aquaporin-4 (AQP-4) and mild hypothermia significantly reduces brain edema formation after intracranial hemorrhage by suppressing the elevation of AQP-4 protein expression." (PMID 22942881, 2012).
ischemic optic neuropathy (2 papers, 2010 to 2022). "As altitudinal hemianopia is highly characteristic of ischemic optic neuropathy, we suggest that an ischemic mechanism mediated by anti-aquaporin-4 antibody may play a role in ON in NMO patients." (PMID 20565857, 2010).
lactic acidosis (2 papers, 2017 to 2024). Metabolic acidosis characterized by the accumulation of lactate in the body. "Recent evidence suggests that lactic acidosis increases Aquaporin-4 protein expression and plasma membrane localization in astrocytes leading to cellular swelling, increased BBB permeability, and subsequent edema." (PMID 29045486, 2017).
Leukoaraiosis (2 papers, 2018 to 2021). "Because nonspecific lesions or leukoaraiosis can be misinterpreted as new lesions in MRI of older AQP4-NMOSD patients, all images were reviewed by NMOSD expert neurologists and neuroradiologists." (PMID 34878547, 2021).
macular edema (2 papers, 2018 to 2022). "Since the water channel AQP4 is located at retinal capillaries and contributes to maintaining the water balance in retinal tissue, AQP4 may be associated with the pathogenesis of DR and macular edema via the increased vascular permeability in the diabetic retina." (PMID 35214116, 2022). "Accordingly, in the eye retina, dexamethasone (used to treat macular edema) selectively upregulated Kir 4.1 (but not AQP-4) channels." (PMID 29506554, 2018).
medulloblastoma (2 papers, 2024). A malignant, invasive embryonal neoplasm arising from the cerebellum. "Activation of Wnt signal is a feature of Medulloblastomas, and embryonic radial glial cells in the neocortex expressing AQP4 are essential for vascular and blood-brain barrier formation by regulating the Wnt signaling pathway." (PMID 38383423, 2024).
muscle atrophy (2 papers, 2011 to 2020). The loss of muscle tissue due to inactivity or disease. "Using a ubiquitination assay, we demonstrated here that overexpression of atrogin 1 induces AQP4 ubiquitination, which is a novel finding indicating that direct targeting of AQP4 by atrogin 1 underlies RCT-induced muscle atrophy." (PMID 32843684, 2020).
myocardial ischemia (2 papers, 2020 to 2021). A disorder of cardiac function caused by insufficient blood flow to the muscle tissue of the heart. "Our findings provided new references for myocardial ischemia-reperfusion injury management via targeting Aqp4-mediated pyroptosis of cardiomyocyte." (PMID 34657556, 2021). "Our findings add new references for Aqp4-mediated myocardial ischemia-reperfusion injury management in future." (PMID 34657556, 2021). "Herein, we further verified the detailed function of AQP4 in the mouse model of myocardial ischemia-reperfusion injury, which mainly via a mechanism of GSDMD-dependent pyroptosis approach." (PMID 34657556, 2021). "Overall, we verified the critical role of Aquaporin 4 inhibition in alleviating the myocardial ischemia-reperfusion injury, which mainly functioned via restraining cardiomyocyte pyroptosis rather than influencing apoptosis." (PMID 34657556, 2021). "Overall, our study lighted the possibility and new option of myocardial ischemia-reperfusion injury management on the basis of Aqp4-mediated pyroptosis in future." (PMID 34657556, 2021).
neurosyphilis (2 papers, 2023 to 2025). Infection of the brain or spinal cord by Treponema pallidum. "In a case of neurosyphilis complicated with AQP4-associated optic neuromyelitis, disease progression was controlled only after treatment with penicillin combined with the administration of immunosuppressive agents." (PMID 37346161, 2023).
neurotoxicity (2 papers, 2020 to 2022). Toxicity that causes injury to the central or peripheral nervous system or damages its function. "Neurotoxicity, disrupted aquaporin 4 (AQP4) polarization, and altered Ca2+ signaling are some of the ways AD-associated gene mutations impede normal astrocyte function, which in turn are proposed to negatively impact neuronal health and function." (PMID 33158189, 2020).
neutropenia (2 papers, 2024 to 2025). A decrease in the number of neutrophils found in the blood. "Their investigations revealed that neutropenia models exhibited reduced AQP-4 loss, persisting for at least 12 h, while neutrophilia exacerbated AQP-4 damage." (PMID 40854886, 2025). "We observed only one AQP4+ patient with persisting neutropenia, which, however, had an absence of SIEs." (PMID 38256489, 2024).
obstructive congenital hydrocephalus (2 papers, 2024 to 2025). "Consistent with this association, 9% of AQP4−/− (knockout, KO) mice offspring have stenosis of aqueduct of Silvio, which causes death during the first month of life due to obstructive congenital hydrocephalus." (PMID 41226330, 2025). "Consistent with this association, Sylvian aqueduct stenosis occurs in 10% of AQP4−/− mice offspring, causing death during the first month of life due to the onset of obstructive congenital hydrocephalus." (PMID 38956598, 2024). "The sporadic occurrence of obstructive congenital hydrocephalus (OH) has been observed in the offspring of AQP4−/− mice generated in the CD1 strain background." (PMID 41226330, 2025). "The sporadic appearance of obstructive congenital hydrocephalus (OCHC) has been observed in the offspring of AQP4−/− mice (KO) due to stenosis of Silvio’s aqueduct." (PMID 38956598, 2024).
prostate carcinoma (2 papers, 2021 to 2024). A carcinoma that arises from epithelial cells of the prostate gland. "As an illustration of this hypothesis, AQP4 is found in prostate cancers, for which zinc has also been identified as an anti-tumor agent." (PMID 38396944, 2024).
rectal cancer (2 papers, 2012 to 2021). A primary or metastatic malignant neoplasm that affects the rectum. "Herein, we reported a case of AQP4‐positive paraneoplastic NMOSD with recurrent rectal cancer and performed a retrospective analysis of previously reported cases and review articles." (PMID 34520629, 2021). "Here, we reported a case of AQP4‐positive paraneoplastic NMOSD related with recurrent rectal cancer and perform a retrospective analysis of previously reported cases." (PMID 34520629, 2021). "Wereported a rare case of AQP4‐IgG positive paraneoplastic NMOSD with recurrent rectal cancer." (PMID 34520629, 2021).
REM sleep behavior disorder (2 papers, 2021 to 2022). A disorder characterized by episodes of vigorous and often violent motor activity during rem sleep (sleep, rem). "They investigated whether AQP4 SNPs were associated with Aβ burden as measured by 18F Florbetapir standard uptake values and examined if AQP4 SNPs moderated the association between REM sleep behavior disorder (RBD) and CSF biomarkers." (PMID 36140362, 2022). "Furthermore, we examined if AQP4 SNPs moderated the association between REM sleep behavior disorder (RBD) and CSF biomarkers." (PMID 35356146, 2021). "Our findings also provide indirect evidence that in PD, AQP4-facilitated clearance of interstitial amyloid might be disrupted in patients with probable REM sleep behavior disorder." (PMID 35356146, 2021).
respiratory failure (2 papers, 2024). The significant impairment of gas exchange within the lungs resulting in hypoxia, hypercarbia, or both, to the extent that organ tissue perfusion is severely compromised. "Aquaporin-4 immunoglobulin G Neuro Myelitis Optica spectrum disorders attacks (NMOSD-AQP4-IgG+ attacks) can cause respiratory failure requiring orotracheal intubation (OTI), but the risk factors and outcomes of OTI during attacks remain unclear." (PMID 38185760, 2024).
schistosomiasis (2 papers, 2015 to 2021). An infectious disease caused by parasitic trematodes of the genus Schistosoma that colonize human blood vessels and release eggs that can cause granulomatous reactions leading to acute (swimmer's itch or acute schistosomiasis syndrome) or chronic disease. "Another independent study revealed that AQP4 has association with the immunoregulation of the liver granuloma formation during schistosomiasis developed by a parasite Schistosoma japonicum in mice." (PMID 33796134, 2021). "In summary, by using AQP4 KO mouse model of schistosomiasis japonica, we demonstrated for the first time an association of AQP4 with the immunoregulation of the liver pathology suggested an important role for AQP4 in regulation of CD4+ T cells differentiation in schistosomiasis." (PMID 25604731, 2015). "Our study for the first time provides evidences that AQP4 has an association with the immunoregulation of the liver granuloma formation, which may confer a new option for schistosomiasis treatment." (PMID 25604731, 2015). "S. japonicum-infected AQP4-null mice with schistosomiasis exhibited greater granulomatous response with increased accumulation of eosinophils, macrophages and Th2 but reduced Th1 and T regulatory cells generation." (PMID 33796134, 2021). "In this study, we showed an enhanced granulomatous response and remarkably increased Th2 but reduced Th1 and Treg cells generation in S. japonicum-infected AQP4 KO mice, which suggests a potential role for AQP4 in the immunoregulation in schistosomiasis." (PMID 25604731, 2015). "In addition, these novel findings imply that AQP4 may function as a new therapeutic target if it is directly involved in Th polarization pathways within immune system cells by modulating CD4+ T cell responses for schistosomiasis or other immune-associated diseases." (PMID 25604731, 2015). "Recently, studies have shown that AQP4 expresses in immune system and lack of AQP4 in mice results in significantly less CD4+CD25+ T regulatory cells (Treg cells) under physiological condition, one of the subpopulations of CD4+T cells which restrains immunopathology in hosts with schistosomiasis." (PMID 25604731, 2015).
scrapie (2 papers, 2012 to 2019). A fatal disease of the nervous system in sheep and goats, characterized by pruritus, debility, and locomotor incoordination. "Our work confirms the upregulation of AQP4 in the preclinical phases of natural ovine scrapie." (PMID 22897917, 2012). "Western blots revealed markedly increased levels of AQP1, AQP4 and AQP9 in the brain tissues of all tested scrapie-infected mice collected at terminal stage." (PMID 31814527, 2019). "In this study using different methodologies, we have demonstrated the overexpressions of AQP1, AQP4 and AQP9 in the brains of several models of scrapie-infected mice during incubation times and at the terminal stage." (PMID 31814527, 2019). "We noticed remarkable enhanced expressions of AQP1, AQP4 and AQP9 in the brains of scrapie-infected animals at the terminal stage." (PMID 31814527, 2019).
Visual impairment (2 papers, 2022 to 2026). "Among patients with significant visual impairment two AQP4+NMOSD patients showed also reduced performance on the SDMT (i.e., < 2 SD below the mean, according to our definition)." (PMID 41493508, 2026). "We found in patients with IIH with visual impairment significantly higher GFAP immunoreactivity (and perivascular AQP4 expression) than in those without visual impairment." (PMID 35903170, 2022).
abducens palsy (1 paper, 2024). "Herein, we report a case of Tolosa-Hunt syndrome presenting with abducens palsy and AQP4 antibodies." (PMID 38419701, 2024).
Acute encephalopathy (1 paper, 2014). "The relationship between pediatric acute encephalopathy and AQP4 is not yet well understood, so further studies will be required to confirm this hypothesis." (PMID 23755112, 2014).
age (1 paper, 2022). A temporal measurement of the time period elapsed since an identifiable point in the life cycle of an organism. "Similarly, AQP4-dependent glymphatic exchange has been implicated in the clearance of tau, and the impairment of this perivascular exchange has been proposed to account in part to the development of age-related and post-traumatic tauopathy." (PMID 35473943, 2022).
alcohol alcoholism (1 paper, 2013). "Ethanol inhibits the expression of AQP4 after acute alcoholism with DAI; AQP4 is upregulated in response to brain edema following DAI with acute alcohol alcoholism." (PMID 24282821, 2013).
Alpers syndrome (1 paper, 2023). A cerebral degeneration that results in progressive degeneration of grey matter in the cerebrum and has_symptom convulsions. "Comparison of individual patients with Alpers’ syndrome to the control group also revealed a significant increased intensity of AQP4 in five of six patients with Alpers’ syndrome (P < 0.01), who showed increased levels of Kir4.1 in previous analyses." (PMID 37259148, 2023). "Group level analysis revealed a significant increase in the intensity of AQP4 in the Alpers’ syndrome patient group compared to the control group in the occipital cortex (P = 0.03)." (PMID 37259148, 2023). "The intensity of AQP4 was also significantly increased in occipital astrocytes from the SUDEP patient group compared to control astrocytes (P < 0.0001), albeit the intensity of AQP4 was significantly higher in most patients with Alpers’ syndrome versus the SUDEP patients (P < 0.05)." (PMID 37259148, 2023). "Furthermore, quantitative analysis of Kir4.1 and AQP4 in frontal cortical astrocytes demonstrated a significantly increased expression (P < 0.05) of these proteins in half of the Alpers’ syndrome patient cohort." (PMID 37259148, 2023). "Since the expression of Kir4.1 is reported to be tightly coupled to AQP4, it is perhaps unsurprising AQP4 protein levels were also frequently increased in astrocytes from patients with Alpers’ syndrome, particularly within the occipital cortex and regions of severe neurodegeneration." (PMID 37259148, 2023). "The abundance of hypertrophic reactive astrocytes displaying signs of mitochondrial dysfunction and altered levels of Kir4.1, AQP4 and glutamine synthetase proteins were more numerous in occipital versus frontal cortical tissues from patients with Alpers’ syndrome." (PMID 37259148, 2023). "Increased AQP4 expression has also been observed in sclerotic hippocampi from patients with TLE, the neuropil of patients with focal cortical dysplasia, and some SUDEP patient cortical astrocytes of the current study, albeit to a lesser extent compared to Alpers’ syndrome patient astrocytes." (PMID 37259148, 2023).
ankylosing spondylitis (1 paper, 2022). An autoimmune chronic inflammatory disorder characterized by inflammation in the vertebral joints of the spine and sacroiliac joints. "However, AQP-4-antibody-positive NMOSD coexisting with ankylosing spondylitis (AS) is rare." (PMID 35864917, 2022).
apraxia (1 paper, 2018). Apraxia is a neurological disorder characterized by the inability to perform tasks or movements, despite having the desire and physical ability to perform them. "Here we report diagonistic apraxia and other symptoms of callosal disconnection syndrome in anti-AQP4-positive NMOSD." (PMID 30147671, 2018).
Arrhythmia (1 paper, 2025). Any cardiac rhythm other than the normal sinus rhythm. "While direct research on AQP4 in astronauts’ cardiac function is limited, prolonged space flight can lead to decreased heart tissue contractility, increased arrhythmias, and higher mortality rates from cardiovascular diseases." (PMID 40650101, 2025).
Ascites (1 paper, 2021). Accumulation of fluid in the peritoneal cavity (between the layers of the peritoneum that lines the abdomen). "TDEE and its diterpenoids can inhibit the reabsorption and concentration of water in the kidneys by reducing the expression levels of AQP1, AQP2, AQP3 and AQP4, thereby resolving ascites." (PMID 33578967, 2021).
autoimmune uveitis (1 paper, 2010). An autoimmune form of uveitis (disease). "We have therefore evaluated the expression of AQP1 and AQP4 on BRB cells during experimental autoimmune uveitis (EAU) in mice." (PMID 20383338, 2010).
Becker muscular dystrophy (1 paper, 2023). Becker muscular dystrophy (BMD) is a neuromuscular disease characterized by progressive muscle wasting and weakness due to degeneration of skeletal, smooth and cardiac muscle. "The same group also provided the first evidence of AQP4 reduction in DMD and Becker’s muscular dystrophy (BMD) patients with different mutations in the dystrophin gene." (PMID 36675000, 2023).
behavioral disorders (1 paper, 2022). "Decreased expression of AQP4 in AQP4+/- mice accelerates the pathological accumulation of αSyn, and the loss of dopamine neurons, and contributes to behavioral disorders." (PMID 36361826, 2022).
benign meningioma (1 paper, 2021). A grade I, slowly growing meningioma. "In conclusion, in this study, we report high AQP4 expression which was significantly correlated with TRPV4 expression in benign meningiomas." (PMID 33538957, 2021).
bowel dysfunction (1 paper, 2024). Any disease in which the causes of the disease is a perturbation of the lower digestive tract leading to its dysfunction. "Among the others, two-thirds of the AQP4+ patients had reported symptoms associated with urinary tract and/or bowel dysfunction, while this was rarer (less than one-third) in MOG+ and double-seronegative patients." (PMID 38256489, 2024).
Cerebellar atrophy (1 paper, 2025). Cerebellar atrophy is defined as a cerebellum with initially normal structures, in a posterior fossa with normal size, which displays enlarged fissures (interfolial spaces) in comparison to the foliae secondary to loss of tissue. "A cerebellar atrophy subtype was specific to AQP4 + NMOSD, whereas a subcortical atrophy subtype was specific to MS." (PMID 40898200, 2025). "Cerebellar atrophy is unique to AQP4 + NMOSD, exhibiting mild brain damage and favorable prognosis." (PMID 40898200, 2025).
cerebral tumours (1 paper, 2010). "In AQP4-null mice, after induction of conditions in which vasogenic oedema forms such as around cerebral tumours and in traumatic brain injury, there is increased brain oedema." (PMID 20860832, 2010). "AQP4 is also upregulated by conditions that induce oedema such as cerebral tumours or cerebral infarction." (PMID 20860832, 2010).
clear cell renal cell carcinoma (1 paper, 2022). "AQP4 was expressed at lower levels in clear cell renal cell carcinoma (fold change = −1.961) and renal oncocytoma (fold change = −6.349) samples than in corresponding normal samples." (PMID 36254092, 2022).
CO poisoning (1 paper, 2016). "In this study, we investigated the effects of N-butylphthalide (NBP) on the expressions of zonula occludens-1 (ZO-1), claudin-5 and aquaporin-4 (AQP-4) proteins in a CO poisoning rat model." (PMID 27833554, 2016). "In the present study, we aimed to investigate the effects of NBP on the ultrastructure changes of BBB and the expressions of AQP-4 and TJ- associated proteins, so as to reveal the underlying mechanisms of neuro-protection and the feasibility of NBP treatment in acute CO poisoning cases." (PMID 27833554, 2016).
coronary artery disease (1 paper, 2018). "Regarding coronary artery disease, AQP4 is involved in cell swelling and cardiac dysfunction in murine myocardial infarction models." (PMID 30563176, 2018).
cortical atrophy (1 paper, 2025). "The findings suggest that cortical atrophy is a common subtype in AQP4 + NMOSD and MS, potentially driven by neuroinflammation, especially in later disease stages." (PMID 40898200, 2025). "As a novel feature, a cortical atrophy subtype of AQP4 + NMOSD was identified." (PMID 40898200, 2025).